SNX21 (sorting nexin family member 21)
Description:
Binds to membranes enriched in phosphatidylinositol 3-phosphate (PtdIns(P3)) and phosphatidylinositol 4,5-bisphosphate. May be involved in several stages of intracellular trafficking.
Synonyms: SNX-L; C20orf161; SNXL; dJ337O18.4; PP3993
Tractability: Antibody: UniProt places it where antibodies can reach, with medium confidence.
Gene: Protein-coding gene on chromosome 20 (45,833,799 to 45,843,276, forward strand). Ensembl gene ENSG00000124104.
Subcellular location: Cytoplasmic vesicle membrane; Early endosome membrane
Subcellular location (Human Protein Atlas): Vesicles; Centriolar satellite
Gene Ontology:
Molecular function: phosphatidylinositol phosphate binding; phosphatidylinositol-3-phosphate binding; phosphatidylinositol-4,5-bisphosphate binding; phosphatidylinositol binding
Biological process: protein transport
Cellular component: cytoplasmic vesicle membrane; early endosome membrane
Genetic constraint (gnomAD): Loss-of-function variants: 36 observed, 27.83 expected, observed/expected ratio (o/e) 1.29, 90% interval 0.99 to 1.7. The upper end of that interval is the gene's LOEUF score, 1.7, which puts it in group 6 of 6, group 1 being the genes least tolerant of losing a copy. Missense variants: 508 observed, 497.84 expected, observed/expected ratio (o/e) 1.02, 90% interval 0.95 to 1.1. Synonymous variants: 218 observed, 212.51 expected, observed/expected ratio (o/e) 1.03, 90% interval 0.92 to 1.15.
Homologues: Orthologues: chimpanzee SNX21 (99% identical), macaque SNX21 (98% identical), mouse Snx21 (91% identical), dog SNX21 (91% identical), guinea pig SNX21 (91% identical), pig SNX21 (91% identical), rabbit SNX21 (87% identical), tropical clawed frog snx21 (47% identical), zebrafish snx21 (43% identical), Drosophila melanogaster Snx21 (24% identical). Paralogues in human: SNX20 (29% identical).
Diseases named in the same sentence as SNX21 in open-access papers:
SNX21 is named in the same sentence as 6 diseases in open-access papers, as found by Europe PMC text mining. Sharing a sentence is not in itself a finding about the gene and the disease. The quoted sentences say what the papers report.
Huntington disease (1 paper, 2021). Huntington disease (HD) is a rare neurodegenerative disorder of the central nervous system characterized by unwanted choreatic movements, behavioral and psychiatric disturbances and dementia. "SNX21 was recently linked to Huntingtin’s trafficking, which could become relevant to further comprehend Huntington’s disease." (PMID 33931804, 2021).
tumor (2 papers, 2017 to 2019). "Although no study revealed the roles of SNX21 in cancer, its family genes, such as SNX1, SNX5 and SNX9 were suggested to be tumor suppressor related." (PMID 31565549, 2019).
SNX21 also shares sentences with these, for which no sentence is quoted: adenocarcinoma (1 paper); cancer (1); gastric cancer (1); neurological disease (1).